MAP3K1 (mitogen-activated protein kinase kinase kinase 1)
Diseases named in the same sentence as MAP3K1 in open-access papers (continued):
Sharing a sentence is not in itself a finding about the gene and the disease.
tumor (continued). "Mutations typically associated with an indolent ER+/luminal A phenotype, such as CDH1 and MAP3K1, were more frequent in MKSlo/ERShi tumours, consistent with previous data." (PMID 37935787, 2023). "An array-based analysis revealed in the second tumor an amplicon at 5q11.2 including MAP3K1 gene and the second one at 11q22.2 containing genes: YAP1 and BIRC2/3, known for its anti-apoptosis function, allowing a comprehensive view of cancer progression." (PMID 35246108, 2022). "Highly mutated genes like BARD1, MALT1, BRCA1/BRCA2, EIF3K, PTEN, FGFR2, and MAP3K1 were also found to overlap with SVs of the tumor sample that were identified by one or more technologies in our study." (PMID 36514120, 2022). "QRT-PCR showed that the expression of the DRAXIN, ITPRID2, and MAP3K1 were significantly upregulated while MOXD1 was downregulated in tumor samples." (PMID 36045691, 2022). "The resultant impairment of MAP3K1 led to defects in pro-survival signaling, which reduced tumor growth and metastasis." (PMID 34404765, 2021). "Meanwhile, A549-exo-treated macrophages significantly increased the level of MAP3K1 in tumor tissues of mice, while this phenomenon was significantly reversed by macrophages treated with A549/miR-770 agomir-exo." (PMID 34195198, 2021). "MAP3K1 is involved in the survival and migration of tumor cells, and MAP3K7 is an important regulator of cell pathways associated with cell proliferation in cancer." (PMID 34638557, 2021). "The tumour-intrinsic factors inversely associated with the reported score such as EGFR, PRKAR1A and MAP3K1 are frequently associated with immune-suppressive phenotypes." (PMID 33139798, 2021). "Tumor cell-derived exosomal miR-770 inhibits M2 macrophage polarization to inhibit the invasion of NSCLC cells via targeting MAP3K1." (PMID 34195198, 2021). "In conclusion, tumor cell-derived exosomal miR-770 inhibits M2 macrophage polarization via targeting MAP3K1." (PMID 34195198, 2021). "Meanwhile, tumor cell-derived exosomal miR-770 inhibited M2 macrophage polarization via downregulation of MAP3K1, which in turn suppressed NSCLC cell invasion." (PMID 34195198, 2021). "The most frequent top mutated genes in tumor fragments of women were USH2A, ATM, IGF2R, MKI67, and MAP3K1 (median variants per sample = 20; missense, nonsense, and splice site mutations)." (PMID 34680380, 2021). "Our study provides mechanistic and in vivo evidence indicating a role for MAP3K1 as a tumor suppressor gene at least in the context of PIK3CA-mutant backgrounds." (PMID 29765551, 2018). "Our findings also suggest that MAP3K1 and MAP2K4 are potential drug targets in combination with MEK inhibitors, in spite of the fact that they are encoded by tumor suppressor genes." (PMID 29795445, 2018). "Although some previous investigations clearly point toward a tumor suppressor role of MAP3K1 in the context of mPIK3CA, overall bibliographic evidence is not conclusive." (PMID 29765551, 2018). "This appears counter-intuitive as MAP3K1 and MAP2K4 are encoded by genes having tumor suppressor-like properties." (PMID 29795445, 2018). "We found that Map3k1 amiRNA conferred marked tumor-suppressive and anti-metastatic effects through stable MEKK1 depletion in vitro and in vivo." (PMID 26759750, 2016). "Mutations in MAP3K1 may affect the activity of the MAPK pathway, thereby influencing the behavior of tumor cells." (PMID 40170854, 2025).
tumor (continued). "The mutation frequency and tumour mutational burden (TMB) of the two groups were calculated using the maftools package in R. The mutation frequencies of PIK3CA, CDH1, GATA3, and MAP3K1 were higher in the “Low-risk” group compared to those of the “Low-risk” group." (PMID 41221278, 2025). "We observed that, compared with Map3k1-WT, Map3k1-mut could significantly promote Tap1/2 mRNA degradation in tumor cells." (PMID 39531335, 2024). "As expected, we found a reduced proportion and inhibited function of CD8+ T cells in Map3k1-mut tumors, which might explain the faster tumor progression of Map3k1-mut tumors compared with Map3k1-WT tumors in vivo." (PMID 39531335, 2024). "Map3k1-mutant tumor cells suppress CD8+ T cell–mediated immunity in vitro." (PMID 39531335, 2024). "To further determine whether Map3k1 regulated surface MHC-I expression via regulation of Tap1/2 expression, we performed a rescue assay by overexpressing Tap1/2 in Map3k1-mut tumor cells." (PMID 39531335, 2024). "Although there is evidence that MAPK pathway blockade, such as MEK inhibitors, could enhance antitumor immune responses, little is known about whether and how MAP3K1 itself modulate s the tumor microenvironment." (PMID 39531335, 2024). "MAP3K1 emerged as a key gene; it was upregulated, an unfavourable prognostic gene according to both Kaplan–Meier and Cox analysis, and showed a positive correlation, suggesting that it was directly influenced by tumour cells." (PMID 39457550, 2024). "In addition, we performed an RNA immunoprecipitation (RIP) assay to compare the ability of DDX17 to bind Tap1/2 mRNAs in Map3k1-WT and Map3k1-Mut tumor cells in the coculture system." (PMID 39531335, 2024). "Interestingly, Map3k1-WT inhibited the tumor growth but Map3k1-Mut displayed the opposite effect on tumor growth in vivo." (PMID 39531335, 2024). "To test whether Map3k1 status in tumor cells can directly impact the function of CD8+ T cells in vitro, we generated 67NR and EMT6 cell lines with varying Map3k1 status that stably present a chicken ovalbumin peptide (OVA257-264)." (PMID 39531335, 2024). "In addition, MAP3K1 is thought to be involved in cell survival, apoptosis, and migration in normal and tumor cells." (PMID 36510163, 2022). "Tumor cell-derived exosomal miR-770 could suppress M2 macrophage polarization via targeting MAP3K1, which in turn decreased NSCLC tumor growth." (PMID 35582534, 2022). "Using correlation of the expression of each tumor to the luminal A and luminal B PAM50 centroids, we found a strong correlation of tumors with both MAP3K1 (mutations/deletions) and PIK3CA mutations with a luminal A-like expression pattern vs. a luminal B expression (p < 0.0001)." (PMID 31552290, 2019). "Consistent with our in vitro and in vivo findings, PDX models having mutations in MAP3K1 or MAP2K4 were significantly more sensitive to binimetinib than their wild type counterparts, with only the mutant tumors showing a decrease in tumor volume over time (p = 0.0023)." (PMID 29795445, 2018). "Firstly, using siRNA, we reduced MAP3K1 expression in two PIK3CA-mutant tumor cell lines (MCF7 and T47D) and in a breast cell line (MCF10A) that had been genetically engineered to express a common PIK3CA (H1047R) mutant (hereafter referred to as MCF10A-PI3KαH1047R)." (PMID 29765551, 2018).
tumor (continued). "Functional mutations in PIK3CA (odds ratio (OR)=0.58; 95% confidence interval (CI)=0.49–0.69), GATA3 (OR=0.77, CI=0.6–0.99), MAP3K1 (OR=0.52, CI=0.4–0.68), KMT2C (OR=0.69, CI=0.52–0.94) and CBFB (OR=0.56, CI=0.38–0.83) were associated with lower grade in ER+ tumours." (PMID 27161491, 2016). "Map3k1 amiRNA-overexpressing tumors displayed very clear tumor border and regular inner structure." (PMID 26759750, 2016). "Moreover, we confirmed that silencing Ddx17 could increase surface MHC-I and OVA antigen expression of Map3k1-mut tumor cells, as measured by both immunofluorescence and flow cytometry, and thus enhanced the activation of CD8+ T cells in the coculture system." (PMID 39531335, 2024). "Similarly, mutations in NLRP1, ALK, and MAP3K1 were frequent among non-responders and tumor mutation count was significantly reduced in post-treatment samples." (PMID 36376989, 2022). "Thus, it is unclear whether MAP3K1 alterations are causal to enhanced sensitivity to PIK3CA antagonists, or if they instead mark a specific tumor phenotype." (PMID 31552290, 2019). "However despite this genomic evidence, the role of MAP3K1 in tumorigenesis is not completely clear, since while several studies support the notion of MAP3K1 having a tumor suppressor role, others have reported that MAP3K1 fuels tumor progression and metastasis." (PMID 29765551, 2018). "By contrast, module 2 and 3, which were only downregulated in EGF-stimulated SHP2WT cells, contained several tumor suppressors, such as NRG1, MAP3K1, CAVIN3, EPHA3/7, CTNNA1/3, and NOTCH3." (PMID 40631144, 2025). "MAP3K1, PPM1D, LMTK3, and TGFB1 levels were significantly elevated across all tumor subtypes, with the highest concentrations consistently observed in TNBC (e.g., TGFB1: 544.92 ± 29.81 pg/mL; MAP3K1: 15.44 ± 0.56 ng/mL)." (PMID 41465262, 2025). "Functionally downstream of MAP3K1 is MAP2K4, another dual-specificity kinase with tumor-suppressive properties via activation of JNK." (PMID 41465262, 2025). "As a result, we observed less presentation of MHC-I and OVA antigen in Map3k1-mut tumor cells compared with the Map3k1-WT group using flow cytometry, in line with the weaker MHC-I fluorescence intensity observed on the surface of Map3k1-mut tumor cells." (PMID 39531335, 2024). "Our study demonstrates that MAP3K1 silencing suppresses the migration of GBM cells, facilitates the TMZ sensitivity and potentially plays a role in anti‐tumour immune regulation." (PMID 39443331, 2024). "In this investigation, it was observed that MAP3K1, MAP3K3, MAP3K5, MAP3K10, and MAP3K15 were upregulated in HCC tumor tissues, whereas MAP3K7, MAP3K8, MAP3K9, and MAP3K11 were downregulated in tumor tissues in GSE14520." (PMID 35311629, 2022). "In case 2, we observed all 5 tumor samples and non-tumor samples had mutations in many of the same genes such as AHNAK2, ZFHX3, KMT2C and MAP3K1." (PMID 41471728, 2025). "Indeed, CEBPB and EP300, along with genes related to the Mitogen-Activated Protein Kinase (MAPK) signaling cascade such as MAP3K1, MAP2K2, and MAP3K11 were significantly upregulated in RMC tumor cells following treatment with nivolumab plus ipilimumab." (PMID 41290625, 2025). "In contrast, there is conservation of MAP3K1 and MAP4K5, which may promote pro-tumor inflammatory response." (PMID 38704802, 2024).
tumor (continued). "MEKK1, the gene product of MAP3K1, is a 196-kDa serine-threonine kinase in the MAPK family with functions in cell viability, apoptosis, and cell motility/migration in multiple normal and tumor cell types." (PMID 39531335, 2024). "Coinciding with the notion, our results identified that amiRNA-mediated MAP3K1 silencing could significantly influence ERK pathway, partially accounting for the impaired tumor growth and metastasis." (PMID 26759750, 2016). "However, we were confronted with a lack of established tumor cell models containing both activating mPIK3CA and inactivating MAP3K1 alterations." (PMID 29765551, 2018).
cancer (104 papers, 2007 to 2026). A tumor composed of atypical neoplastic, often pleomorphic cells that invade other tissues. "Associations with SPTA1, PIK3CA, and MAP3K1 mutations suggest the role of DDIT3 in diverse pathways in cancer progression." (PMID 38911383, 2024). "GWAS and case–control association studies have shown that SNPs in the MAP3K1 gene influence the development and progression of cancer in patients." (PMID 36560873, 2023). "The present study concludes that MAP3K1 gene rs889312 polymorphism plays a prognostic role in the survival of cancer patients." (PMID 36560873, 2023). "Accumulating studies have evaluated the association between MAP3K1 polymorphisms and cancer prognosis." (PMID 36560873, 2023). "To date, a wide variety of studies have explored the correlation between the MAP3K1 rs889312 variant and the risk of cancer progression or prognosis." (PMID 36560873, 2023). "We have focused on the studies that evaluated the correlation between survival outcomes of cancer patients and MAP3K1 rs889312 polymorphism and tried to develop rs889312 as a prognostic marker." (PMID 36560873, 2023). "MAP3K1 is frequently mutated in human cancers, and mutations of this gene are the second-most prevalent genetic variation in BC." (PMID 38003265, 2023). "This is, to the best of our knowledge, the first systematic meta‐analysis to evaluate the influence of MAP3K1 rs889312 polymorphism on cancer prognosis." (PMID 36560873, 2023). "In patient 8, two cancer gene mutations (a MAP3K1 frameshift deletion and a KDM6A frameshift insertion) were identified only in the primary tumor, suggesting both were later molecular events in the primary tumor acquired after the spread of metastatic clones." (PMID 33148332, 2020). "IntClusts 2 and 6 are relatively small subgroups comprising ER+ cancers with poor outcome, but MAP3K1 mutations in IntClust2 (median=1, IQR=0.91–1, seven mutations) were present in higher CCFs than in IntClust6 (median=0.90, IQR=0.69–0.99, six mutations)." (PMID 27161491, 2016). "Out of these SNPs, several occur in genes associated with behavior (Scn10A), metabolism (Ppgca1b), cancer (Brca2), and immune response (Map3k1, OAS2, IL18R1)." (PMID 21668978, 2011). "Similarly, in our BCa study, mutual exclusivity between PIK3CA and MAP3K1 mutations and the loss of 13q14.2 raises intriguing questions about the functional redundancy or compensatory mechanisms within cancer cells." (PMID 39605038, 2024). "The present study results indicated that MAP3K1 rs889312 polymorphism might be associated with poor OS in cancer patients." (PMID 36560873, 2023). "Our findings suggest that cancers having mutations in MAP3K1 or MAP2K4, which are frequent in tumors of breast, prostate and colon, may respond to MEK inhibitors." (PMID 29795445, 2018). "Second, we did not investigate the association between genetic variations in MAP3K1 rs889312 and patients’ responses to anti-cancer drugs, primarily because different chemotherapies were employed in our patients which results in a lack of statistical power to detect responses to drug effects." (PMID 24759887, 2014). "This hypothesis was highlighted primarily by the identification of risk variants at the FGFR2 and MAP3K1 loci – two genes known to be somatically altered in human cancer and whose products are involved in signal transduction among other processes." (PMID 19094230, 2008). "The high rate of MAP3K1 LoF mutations in ER-positive BrCa patients (frequently mPIK3CA) suggest that pathway cross-talk might be important in tumorigenesis or response to anti-cancer therapeutics." (PMID 29765551, 2018).